PML (PML nuclear body scaffold)
Diseases named in the same sentence as PML in open-access papers (continued):
Sharing a sentence is not in itself a finding about the gene and the disease.
triple-negative breast carcinoma (12 papers, 2013 to 2025). An invasive breast carcinoma which is negative for expression of estrogen receptor (ER), progesterone receptor (PR), and human epidermal growth factor receptor 2 (HER2). "We examined PML chromatin association in triple-negative breast cancer (TNBC) cell lines, where it exerts important oncogenic functions." (PMID 37823593, 2023). "Although the complete or partial loss of functional PML is a hallmark for various tumors, higher expression of PML has also been reported in tumors such as ovarian carcinoma and triple-negative breast cancer (TNBC)." (PMID 33546431, 2021). "A recent study verified that PML was upregulated in triple negative breast cancer and knockdown PML suppressed tumor growth in vitro and in vivo." (PMID 36776317, 2023). "We and others have demonstrated that PML is overexpressed in triple-negative breast cancer (TNBC) where it displays oncogenic functions by promoting pro-tumoral metabolism, cancer stem cell maintenance and metastasis." (PMID 37823593, 2023). "It has been shown that PML is up-regulated in triple negative breast cancer (TNBC) and regulates cancer-initiating cell function." (PMID 36418345, 2022). "Similarly, PML stimulates metabolic fueling (lipids, ATP) of cancer cells, and high PML expression correlates with poor prognosis in triple-negative breast cancers." (PMID 37382966, 2023). "Additionally, since PML contributes to hematopoietic cancer stem cell self-renewal and the aggressiveness of triple-negative breast cancer, directly reducing PML protein levels seems to be a promising strategy to treat some types of cancers." (PMID 29416846, 2018). "A PML–PPAR–fatty acid oxidation axis fuels asymmetric division and normal hematopoietic stem cell pool maintenance or triple-negative breast cancer survival." (PMID 37382966, 2023). "We have previously reported that the Promyelocytic Leukemia protein (PML) is upregulated in triple negative breast cancer (TNBC) and it regulates cancer-initiating cell function, thus suggesting that this protein can be therapeutically targeted in combination with PML-based stratification." (PMID 31570853, 2020). "On the basis of these findings it is tempting to speculate that targeting both PML and FAO in triple-negative breast cancer tumors with combinations of ATO and other targeted therapies may present a novel approach to treating this tumor subtype." (PMID 23936764, 2013). "Moreover, the regulation of cancer-initiating cell (CIC) and metastatic potential is restricted to PML high-expressing estrogen receptor-negative breast tumors, predominantly triple negative breast cancer (TNBC)." (PMID 31570853, 2020).
glioblastoma (11 papers, 2016 to 2024). The most malignant astrocytic tumor (WHO grade IV). "Our in silico simulations suggest that the underlying mechanism of PML-driven Glioblastoma physiology regulates invasion by differential modulation of the cell-to-cell adhesive and diffusive capacity of the cells." (PMID 34208139, 2021). "However, exposure of PriGO8A primary glioblastoma cells to media with 10% serum induced a senescence-like phenotype characterized by increased senescence-associated β galactosidase activity, PML bodies and p21 and morphological changes typical of senescence." (PMID 28526854, 2017). "Recent evidence indicates dysregulation of the expression of the Promyelocytic Leukemia Protein (PML) in primary Glioblastoma samples." (PMID 34208139, 2021). "The role of PML in Glioblastoma progression has recently gained attention due to its controversial effects in overall Glioblastoma evolution." (PMID 34208139, 2021). "It has also been suggested that PML mediates glioblastoma resistance to the mammalian target in rapamycin-targeted therapies." (PMID 26897165, 2016). "In this work, we studied the role of PML in Glioblastoma pathophysiology using the U87MG cell line." (PMID 34208139, 2021). "Under the light of precision medicine where variation in the expression levels of PML within a tumor and/or across different patients is expected, exploring the differential expression and effect of PML in patient-derived glioblastoma cell lines comprises an important next step." (PMID 34208139, 2021). "In the brain, PML participates in the physiological migration of the neural progenitor cells, which have been hypothesized to serve as the cell of origin of Glioblastoma." (PMID 34208139, 2021). "Indeed, knockdown of PML or treatment of glioblastoma cells with the PML degradation agent, arsenic trioxide, inhibited cancer stem cell growth as well as glioblastoma tumor growth in a mouse xenograft model." (PMID 29416846, 2018). "Arsenic trioxide, which promotes PML degradation, has long been used as an APL treatment and, recently, it has been repurposed for other cancer types such as osteosarcoma and glioblastoma." (PMID 38752489, 2024). "In addition, the removal of PML leads to senescence induction also in TNBC and glioblastoma." (PMID 38730056, 2024).
herpesvirus infection (11 papers, 2009 to 2026). "Associated with viral DNA after its nuclear deposition, PML bodies are composed of a set of interferon-inducible proteins that play important roles in host anti-viral defense during herpesvirus infection." (PMID 23807710, 2013). "Taken together, our data demonstrate an important role of BNRF1 in supporting EBV early infection by interacting with Daxx and ATRX; and suggest that tegument disruption of PML-NB-associated antiviral resistances is a universal requirement for herpesvirus infection in the nucleus." (PMID 22102817, 2011). "PML bodies have been extensively studied in the context of herpesvirus infection, where they play a role in T1 IFN signaling." (PMID 41461613, 2026). "During herpesvirus infection, PML-NBs induce epigenetic silencing of viral genomes, however, this defense is antagonized by viral regulatory proteins such as IE1 of human cytomegalovirus (HCMV)." (PMID 35319461, 2022). "It is becoming evident that PML has independent roles in the regulation of intrinsic and innate immune defences during herpesvirus infection." (PMID 30901352, 2019). "Here we report that HIRA displays spatiotemporally distinct kinetics of recruitment to infecting HSV-1 genomes and PML-NBs, which independently contribute to the regulation of intrinsic and innate immune defences in response to herpesvirus infection." (PMID 30901352, 2019). "One aspect of cellular restriction of herpesvirus infections is mediated by components of nuclear structures known as PML nuclear bodies (PML NBs), or ND10." (PMID 27535048, 2016). "During herpesvirus infection, PML plays an essential role in intrinsic suppression of the viral genome." (PMID 25812002, 2015). "RNAi-mediated depletion of PML NB proteins has revealed several examples of herpesvirus infections that are restricted by one or more PML NB components, and in these cases the viruses express regulatory proteins that overcome the restriction." (PMID 23825941, 2013). "PML-NBs (nuclear bodies) or ND-10 are storage warehouses for sumoylated proteins, which negatively regulate herpesvirus infection, as part of the intrinsic immune response." (PMID 23990779, 2013). "As a core component of PML NBs, PML plays a critical role in limiting herpesvirus infections." (PMID 39823515, 2025). "Characterization of the intrinsic immune function of PML-NBs during herpesvirus infection has identified the major components PML, Sp100, Daxx, and ATRX as independent restriction factors that induce epigenetic silencing of viral DNA by recruiting chromatin-modifying enzymes." (PMID 35319461, 2022). "Recent studies have shown that the HIRA (histone cell cycle regulator) histone H3.3 chaperone complex, composed of HIRA, Ubinuclein 1 (UBN1), and Calcineurin-binding protein 1 (CABIN1), relocalizes to PML-NBs in response to replication-defective herpesvirus infection." (PMID 30901352, 2019). "The degree of restriction imparted by any one PML NB protein may be modest, but there is evidence that PML NB–mediated inhibition of herpesvirus infections involves the cooperative actions of several PML NB components." (PMID 23825941, 2013). "However, in this context it is of note that recent publications demonstrate an influence of herpesvirus infections on the splicing pattern of PML suggesting diverse roles for the individual PML isoforms with regard to viral replication." (PMID 21994592, 2009). "Importantly, none of these hypothesises are mutually exclusive and further studies are required to identify the role(s) of PML and PML-NBs in the HIRA-dependent induction of ISG expression during herpesvirus infection." (PMID 30901352, 2019). "Intriguingly, PML bodies appear to be interconnected with the DNA break repair pathway and the DNA sensor IFI16, which activates the STING–T1 IFN pathway during herpesvirus infections." (PMID 41461613, 2026).
herpesvirus infection (continued). "ICP0 induces the degradation or disrupts the functions of several PML NB components, for example, PML, Sp100, hDaxx, and ATRX (12, –, 16), each of which has been shown to have a role in restricting herpesvirus infections." (PMID 27535048, 2016). "Our research uncovers distinct kinetics in the spatiotemporal recruitment of HIRA to infecting viral genomes and PML-NBs during different phases of HSV-1 infection and identifies dual roles for HIRA in the sequential regulation of intrinsic and innate immunity to herpesvirus infection." (PMID 30901352, 2019).
lymphoma (11 papers, 2012 to 2024). A malignant (clonal) proliferation of B- lymphocytes or T- lymphocytes which involves the lymph nodes, bone marrow and/or extranodal sites. "Importantly, loss of one or both allele of PML significantly accelerates lymphoma development in Eμ-myc mice model, supporting the contribution of PML elevation to the suppression of lymphomagenesis observed in Eμ-myc/E6AP+/− mice." (PMID 22935031, 2012). "For example, loss of the normal function of TRIM19/PML through translocation or E6AP-mediated degradation is implicated in the pathogenesis of APL, B-ALL and lymphoma, whereas in CML low TRIM19 expression correlates with improved overall survival." (PMID 29110249, 2018). "Furthermore, microarray analyses of PML mRNA expression showed complete loss of or strongly reduced PML transcript expression in many different human neoplasms, including colon, prostate, and breast adenocarcinomas, as well as in lung, CNS, germ cell, and non-Hodgkin’s tumors/lymphomas." (PMID 29888200, 2018). "PML knock-out mice develop a range of cancers including papillomas, carcinomas, and lymphomas after exposure to carcinogens." (PMID 29888200, 2018). "A role for PML in lymphoma was further demonstrated using mouse models of myc-driven B-lymphoma." (PMID 29110249, 2018). "Consistent with a role of E6AP in PML degradation, lymphoma cells and premalignant B-lymphoid cells derived from Eμ-myc/E6AP+/− mice exhibit elevated levels of PML and PML-NBs compared with those cells derived from Eμ-myc mice." (PMID 22935031, 2012).
myeloid leukemia (11 papers, 2006 to 2023). A clonal proliferation of myeloid cells and their precursors in the bone marrow, peripheral blood, and spleen. "In adult myeloid leukemias we found significant associations between the variant allele of PML_rs9479 and decreased AML risk (OR = 0.61 (0.38-0.97), and between variant alleles of IRF8_ rs10514611 and ARHGAP26_rs187729 and increased CML risk (OR = 2.4 (1.12-5.15) and 1.63 (1.07-2.47), respectively)." (PMID 24886876, 2014). "Chromosome 8q24 has an equivalent in mice (chromosome 15), which is the most commonly recurring abnormality in PML-RARα transgenic mice, and it cooperates with PML-RARα to accelerate the development of myeloid leukemia." (PMID 26545364, 2015). "Since the previously unknown region of chromosome 15 was designated as myl (from myelocytic leukemia), one of the outdated synonyms for PML is MYL." (PMID 38069029, 2023). "PML and PML bodies are not only affected in myeloid leukemia." (PMID 33120984, 2020). "The fusion protein PML-RARA is associated exclusively with myeloid leukemia in both humans and mice (unlike BCR-ABL and MLL fusion proteins, which can lead to myeloid or lymphoid leukemias)." (PMID 23056333, 2012). "It is worth nothing that ATRA is also able to promote autophagy and differentiation in myeloid leukemia HL60 cells that do not express PML-RARα, supporting the idea that PML-RARα degradation is not the sole mechanism through which autophagy promotes differentiation in response to ATRA." (PMID 31330838, 2019).
osteosarcoma (11 papers, 2009 to 2024). A usually aggressive malignant bone-forming mesenchymal neoplasm, predominantly affecting adolescents and young adults. "Disrupting LAPS by CRISPR/Cas9 knockout of the PML gene in human U2OS osteosarcoma cells (PML KO) resulted in fewer nLDs that were deficient in CCTα, Lipin1, and DAG, resulting in decreased PC and TAG synthesis." (PMID 32461215, 2020). "The selected 5 MAGs (MAP3K5, PML, WDR1, BAMBI, and GNPDA2) were identified as prognostic-related genes for osteosarcoma, and a novel macrophage-associated risk model was constructed based on these 5 MAGs." (PMID 34188683, 2021). "In general, 5 MAGs (MAP3K5, PML, WDR1, BAMBI, and GNPDA2) correlated with the prognosis of osteosarcoma were screened for the construction of the risk model." (PMID 34188683, 2021). "PML was stably silenced in U2OS osteosarcoma cells and TERT-immortalized normal human diploid fibroblasts (NHDF) using a previously well characterized short-hairpin RNA28 (shPML-A)." (PMID 28332630, 2017). "We also characterized U2OS human osteosarcoma cells expressing Clover-tagged PML and demonstrate that this strategy generates cell lines with PML NBs that are structurally and functionally similar to bodies in the parental cell line." (PMID 26429972, 2015). "To identify potential cytoplasmic PML targets, we have analysed the subcellular distribution of different PML isoforms containing a mutated NLS6 in the osteosarcoma cell line U2OS." (PMID 21092142, 2010). "Here, we reported that high expression of PML might inhibit osteosarcoma growth, which was also consistent with these findings." (PMID 34188683, 2021). "Therefore, we detected the presence of APBs by co-localization of PML with TRF2 in various T24 cells at different passages compared with the osteosarcoma cell line U2OS." (PMID 22110753, 2011). "Gene WDR1 (p = 0.003), PML (p = 0.002), MAP3K5 (p < 0.001), and GNPDA2 (p = 0.030) showed a better prognosis of osteosarcoma in the high expression group." (PMID 34188683, 2021). "The expression of gene WDR1 (p = 0.006), PML (p = 0.005), MAP3K5 (p = 0.010), and GNPDA2 (p = 0.009) were significantly higher in normal bone sample while in osteosarcoma samples, the expression of BAMBI (p = 0.006) was significantly higher." (PMID 34188683, 2021). "In osteosarcoma Saos-2 cells, the colocalization of a DAXX double SIM mutant and a PML mutant lacking SUMOylation sites was severely impaired, further supporting the importance of PML SUMOylation and the SIM–SUMO interaction in tethering DAXX to PML-NBs." (PMID 31350900, 2019). "Expression data for U2OS cells were also included in the CCLE osteosarcoma cell line data and, although the data was not significant (p = 0.130), DDIT4 showed a positive correlation with PML (Spearman’s r = 0.312), consistent with our observations in this study." (PMID 28332630, 2017).
ovarian carcinoma (10 papers, 2012 to 2024). A malignant neoplasm originating from the surface ovarian epithelium. "We also demonstrate that the chromosomal locus containing the DDIT4 gene is directly associated with PML NBs, and that DDIT4 and PML expression levels are significantly correlated in several solid tumours including breast, lung and ovarian cancers." (PMID 28332630, 2017). "In addition, PML expression and its aggregation into PML-NBs was linked to increased oxidative phosphorylation and reactive oxygen species in a subtype of ovarian cancer." (PMID 38730056, 2024). "In our previous study, we found that DAXX co-localized with PML in ovarian cancer cells and mouse ovarian surface epithelium (mOSE)." (PMID 30336783, 2018). "Also, persistent oxidative stress leads to the accumulation of promyelocytic leukemia protein (PML)-nuclear bodies in ovarian carcinomas, resulting in activation of the transcriptional co-activator PPARγ coactivator-1α (PGC-1α)." (PMID 32185131, 2020). "In ovarian cancer cells, DAXX interacts with promyelocytic leukemia protein and is localized to nuclear bodies PML in the subnuclear domain." (PMID 36875159, 2023). "Collectively, our data establish a stress-mediated PML-PGC-1α-dependent mechanism that promotes OXPHOS metabolism and chemosensitivity in ovarian cancer." (PMID 30244973, 2019).
latent infection (9 papers, 2008 to 2023). "We have previously shown that PML bodies are disrupted by latency‐associated expression of viral LUNA during HCMV latent infection." (PMID 38009611, 2023). "Here we show that EBV latent infection in NPC cells is associated with the disruption of host PML nuclear bodies (NBs) and that EBNA1 is entirely responsible for this effect." (PMID 18833293, 2008). "We found that EBNA1 is partly associated with PML NBs in a native latent infection in NPC cells and can physically associate with at least one PML isoform that appears to be PML IV." (PMID 18833293, 2008). "In contrast, HCMV disrupts PML NBs during both lytic and latent infection but via different mechanisms." (PMID 38009611, 2023). "As the core component of PML-NBs, PML is an important host-defense molecule that inhibits early herpes virus infection and favors the establishment of latent infection." (PMID 36680047, 2022). "This disruption occurs both in the context of a native latent infection and when exogenously expressed in EBV-negative NPC cells and involves loss of the PML proteins." (PMID 18833293, 2008). "Considering the role of PML in the process of latent infection with the herpes virus, these early high levels of IFN-γ and PML expression in chickens infected with MDV/RB1B could drive latent infection to occur earlier." (PMID 36680047, 2022). "HIRA complex colocalizes with the PML-NBs in senescent cells, and during HSV-1 latent infection, HIRA is involved in the repression of the viral genome." (PMID 34208020, 2021). "As a ubiquitin E3 ligase, HSV1 ICP0 preferentially targets the SUMO-modified TRIM19/PML isoforms, leading to their degradation, among its many roles in HSV1 lytic and latent infection." (PMID 33670221, 2021). "For instance, latent infection with HSV-1 does not lead to the disruption of PML bodies; this only occurs as the lytic cascade is initiated with the expression of ICP0." (PMID 37766281, 2023). "However, during latent infection, in the absence of IE72 expression, PML bodies are also disrupted but this is mediated by the de‐SUMOylase activity of LUNA." (PMID 38009611, 2023).